SBDSP1 (SBDS pseudogene 1)
Synonyms: formerly SBDSP
Gene: Transcribed unprocessed pseudogene on chromosome 7 (72,829,656 to 72,836,701, forward strand). Ensembl gene ENSG00000225648.
Diseases named in the same sentence as SBDSP1 in open-access papers:
SBDSP1 is named in the same sentence as 3 diseases in open-access papers, as found by Europe PMC text mining. Sharing a sentence is not in itself a finding about the gene and the disease. The quoted sentences say what the papers report.
colon cancer (1 paper, 2020). "One group showed that lncRNA SBDSP1 is elevated in colon cancer tissues and further correlates with differentiation, invasion depth, TNM stage, and survival time in colon cancer patients." (PMID 33246471, 2020).
colorectal cancer (1 paper, 2021). A primary or metastatic malignant neoplasm that affects the colon or rectum. "The pseudogene‐derived lncRNA SBDSP1 has been shown to suppress tumor growth and invasion and is related to poor outcomes in colorectal cancer." (PMID 33660378, 2021).
SBDSP1 also shares sentences with these, for which no sentence is quoted: tumor (1 paper).